METTL3 (methyltransferase 3, N6-adenosine-methyltransferase complex catalytic subunit)
Diseases named in the same sentence as METTL3 in open-access papers (continued):
Sharing a sentence is not in itself a finding about the gene and the disease.
blood cancers (4 papers, 2019 to 2024). "Therefore, in our present review, we focus on the structure of METTL3, the role of METTL3 in both normal and malignant hematopoiesis, and the potential of METTL3 for treating hematological neoplasms." (PMID 35574332, 2022). "Moreover, METTL3 strongly impacts the process and development of hematological neoplasms, including the differentiation, apoptosis, proliferation, chemoresistance, and risk of tumors." (PMID 35574332, 2022).
immune diseases (4 papers, 2024 to 2025). "This review establishes a theoretical basis for considering METTL3 as a novel regulator, an important diagnostic biomarker, and a potential target for treating immune dysfunctions." (PMID 40196133, 2025). "Therefore, based on these findings, we propose that the dysregulation of METTL3 may serve as an underlying trigger for immune system disorders." (PMID 39416774, 2024). "However, a thorough review and analysis of this evidence is currently missing, which limits the understanding of METTL3's mechanisms and significance in immune dysfunctions." (PMID 40196133, 2025). "Moreover, reduced expression levels of DNMT3A, METTL3, and YTHDF1 were associated with immune diseases or immune signalling pathways." (PMID 39485681, 2024).
retinopathy (3 papers, 2023 to 2024). "Conversely, METTL3 ablation in a hypoxia-induced retinopathy model results in reduced avascular regions, diminished pathological neovascular tufts, and inhibition of alkali burn-induced corneal neovascularization (CNV)." (PMID 39834386, 2024). "Knockdown of m6A writer METTL3 can reduce pathological neovascularization in both oxygen-induced retinopathy model and corneal alkali burn model." (PMID 37355654, 2023).
colon (2 papers, 2022 to 2024). "Indeed, METTL3 is upregulated in a variety of digestive system cancers." (PMID 35484099, 2022).
gynecologic tumors (2 papers, 2021 to 2023). "Recent studies have confirmed that m6A is associated with a wide spectrum of biological processes and it significantly affects disease progression and prognosis of patients with gynecologic tumors, in which the role of Mettl3 cannot be ignored." (PMID 37007040, 2023). "However, the current research on Mettl3 inhibitors is mostly focused on hematological malignancies, and there are no research reports of Mettl3 inhibitors in gynecologic tumors; thus, further investigation is warranted." (PMID 37007040, 2023).
infectious disease (2 papers, 2023 to 2024). A disorder directly resulting from the presence and activity of a microbial, viral, or parasitic agent in humans. "Preclinical investigations have suggested the therapeutic viability of targeting METTL3 in oncology, autoimmune pathologies, and infectious diseases." (PMID 39416774, 2024). "In the following sections, we elaborate on the mechanism of action of METTL3 and its effects on m6A reading proteins in cardiovascular, metabolic, degenerative, immune, infectious diseases, and tumors." (PMID 37671161, 2023). "Here, we summarize the expression changes, modified target genes, and pathogenesis related to METTL3 in cardiovascular, metabolic, degenerative, immune, and infectious diseases, as well as tumors." (PMID 37671161, 2023).
musculoskeletal diseases (2 papers, 2020 to 2023). "With increased research into m6A modification, the biological functions of the METTL3-METTL14 complex in musculoskeletal diseases have been extensively studied." (PMID 37202385, 2023). "Recently, accumulating evidence has indicated that the METTL3-METTL14 complex plays a key role in musculoskeletal diseases in an m6A-dependent or -independent manner." (PMID 37202385, 2023). "In the following section, we will discuss recent studies of the role of the METTL3-METTL14 complex in certain musculoskeletal diseases, such as OP, OA, RA and OS." (PMID 37202385, 2023). "This review introduces the main features of the METTL3-METTL14 complex and its working mechanism in m6A modification and summarizes recent progress in understanding the role of the METTL3-METTL14 complex in certain musculoskeletal diseases, such as OP, OS, RA and OA." (PMID 37202385, 2023). "In summary, m6A-modifying proteins can serve as potential targets for drugs with which the FTO and METTL3 inhibitor may have great prospect in the treatment of musculoskeletal disorders." (PMID 32984346, 2020).
reproductive diseases (2 papers, 2024). "In contrast, despite numerous studies demonstrating the therapeutic potential of targeting either METTL3 or its associated signalling pathways for reproductive diseases, there is still a scarcity of credible clinical data supporting this approach." (PMID 38332508, 2024).
respiratory diseases (2 papers, 2025). "This study uncovered a novel link between epigenetic modification, mitophagy, and ferroptosis, identifying METTL3-mediated m6A modification and mitophagy as potential targets for preventing PM2.5-related respiratory diseases." (PMID 41142801, 2025). "Further elucidation of METTL3’s interactions with its downstream targets and signaling pathways in specific lung cell populations will be essential to develop effective and personalized therapeutic strategies for ALI/ARDS and related respiratory disorders." (PMID 41515964, 2025).
brain disorder (1 paper, 2023). A disease affecting the brain or part of the brain. "We also suggest future study directions, such as exploring the roles and mechanisms of METTL3 in microglia and developing brain disorders." (PMID 37189411, 2023). "Apart from involvement in tumors, degenerative disorders, and brain injuries, METTL3 has also been reported to be involved in other brain disorders." (PMID 37189411, 2023).
hematological cancers (1 paper, 2025). "With the first-in-class METTL3 inhibitor STC-15 now in early-phase clinical trials in solid tumours (NCT05584111, NCT06975293), and additional RNA-modifying enzyme inhibitors advancing preclinically, these pathways are emerging as therapeutically tractable, including in hematological cancers." (PMID 40973767, 2025).
movement disorder (1 paper, 2018). Neurological conditions resulting in abnormal voluntary or involuntary movement, which may impact the speed, fluency, quality and ease of movement. "It is tempting to speculate that the developmental defects in the cerebellums caused by depletion of METTL3 might contribute to the movement disorders of the cKO pups." (PMID 29879109, 2018).
vascular disorder (1 paper, 2024). A general term used to describe any disease affecting blood vessels]. "Therefore, we propose that METTL3 serves as a potential diagnostic biomarker and therapeutic target for EC dysfunction-related vascular disorders." (PMID 39834386, 2024). "Moreover, advancing our understanding of METTL3’s role in developmental angiogenesis could provide insights into congenital vascular disorders and potential therapeutic approaches for these conditions." (PMID 39834386, 2024).
METTL3 also shares sentences with these, for which no sentence is quoted: acute respiratory distress syndrome (4 papers); colorectal (4); preeclampsia (3); alopecia (2); bone disorder (2); chronic obstructive pulmonary disease (2); conjunctival melanoma (2); cutaneous melanoma (2); ductal adenocarcinoma (2); endocervical adenocarcinoma (2); Huntington disease (2); hypertrophy (2); idiopathic pulmonary fibrosis (2); membranous nephropathy (2); mental illnesses (2); multiple myeloma (2); polycystic kidney (2); rectal cancer (2); rectum adenocarcinoma (2); skin cancer (2); T-Cell Lymphoma (2); thymoma (2); acinar cell carcinoma (1); acute myocardial infarction (1); allergic rhinitis (1); amyloid (1); amyotrophic lateral sclerosis (1); ankylosing spondylitis (1); arteriovenous malformation (1); Ataxia (1).
A further 69 diseases each share a sentence with METTL3 in 1 paper.